CDKL2 (cyclin dependent kinase like 2)
Synonyms: P56; KKIAMRE
Tractability: Small molecule: a structure with a bound ligand is known; a high-quality ligand is known; it belongs to a druggable protein family. PROTAC: a small molecule that binds it is known.
Target class: Protein Kinase; CMGC protein kinase CDKL family; CMGC protein kinase group; Enzyme; Kinase
Chemical probes: SGC-CDKL2/AAK1/BMP2K-1 (high quality)
Gene: Protein-coding gene on chromosome 4 (75,576,494 to 75,630,716, reverse strand). Ensembl gene ENSG00000138769.
Subcellular location: Cytoplasm; Nucleus
Subcellular location (Human Protein Atlas): Centrosome; Nucleoplasm
Gene Ontology:
Molecular function: protein binding; protein kinase activity; ATP binding; cyclin-dependent protein serine/threonine kinase activity; protein serine kinase activity
Biological process: sex differentiation; signal transduction; regulation of cell cycle
Cellular component: nucleoplasm; cytoplasm; nucleus
Genetic constraint (gnomAD): Loss-of-function variants: 30 observed, 33.27 expected, observed/expected ratio (o/e) 0.9, 90% interval 0.67 to 1.22. The upper end of that interval is the gene's LOEUF score, 1.22, which puts it in group 5 of 6, group 1 being the genes least tolerant of losing a copy. Missense variants: 414 observed, 437.81 expected, observed/expected ratio (o/e) 0.95, 90% interval 0.87 to 1.03. Synonymous variants: 129 observed, 151.14 expected, observed/expected ratio (o/e) 0.85, 90% interval 0.74 to 0.99.
Homologues: Orthologues: chimpanzee CDKL2 (99% identical), macaque CDKL2 (97% identical), rabbit CDKL2 (91% identical), pig CDKL2 (87% identical), dog CDKL2 (87% identical), mouse Cdkl2 (85% identical), rat Cdkl2 (84% identical), guinea pig CDKL2 (81% identical), tropical clawed frog cdkl2 (61% identical). Paralogues in human: CDKL3 (40% identical), CDKL5 (34% identical), CDKL1 (33% identical), CDKL4 (30% identical), CDK13 (24% identical), CDK12 (23% identical), CDK1 (22% identical), CDK2 (21% identical), CDK8 (21% identical), CDK19 (21% identical), CDK3 (21% identical), CDK5 (21% identical), and 14 more.
Diseases named in the same sentence as CDKL2 in open-access papers:
CDKL2 is named in the same sentence as 31 diseases in open-access papers, as found by Europe PMC text mining. Sharing a sentence is not in itself a finding about the gene and the disease. The quoted sentences say what the papers report.
breast carcinoma (6 papers, 2014 to 2021). "Notably, CDKL2 is expressed significantly higher in mesenchymal human breast cancer cell lines than in epithelial lines, and its over-expression/amplification in human breast cancers is associated with shorter disease-free survival." (PMID 25333262, 2014). "To date, only one published study by Li and colleagues revealed the involvement of CDKL2 in cancers, wherein they reported that expression of CDKL2 was remarkably higher in human breast cancer tissues and cells than that in their normal counterparts." (PMID 35096961, 2021). "Their results suggested that CDKL2 serves as a carcinogenic gene in breast cancer, promoting epithelial-mesenchymal transition and tumor progression." (PMID 35096961, 2021). "CDKL2 and GRK3 have been implicated in breast cancer progression and their overexpression correlates with poor prognosis." (PMID 31941153, 2020). "CDKL2 was indeed expressed significantly higher in mesenchymal breast cancer lines than in epithelial (luminal and basal) breast cancer lines (average fold change = 8.0, P = 0.00005)." (PMID 25333262, 2014). "In orthotopic breast cancer xenograft model, expression of CDKL2 gene significantly increased tumor incidence and spontaneous metastasis." (PMID 25333262, 2014). "Results from our orthotopic xenograft model also indicated that CDKL2 promoted breast cancer progression, which suggests that CDKL2 expression may be higher in human breast cancers with poorer prognostics." (PMID 25333262, 2014). "Furthermore, CDKL2 enhanced primary tumor formation and metastasis in a breast cancer xenograft model." (PMID 25333262, 2014). "Interestingly, two human bone marrow derived mesenchymal stem cells (MSC-1 and -2), human lung fibroblast WI-38 and immortalized human foreskin fibroblast BJ-hTERT+LT also expressed CDKL2 at a much higher level than epithelial breast cancer lines with an average fold change of 26.5." (PMID 25333262, 2014). "Finally, we observed that CDKL2 is expressed significantly higher in mesenchymal subtypes of breast cancer cells, human MSC and fibroblasts than in epithelial subtypes (luminal and basal) of breast cancer cells, which strongly supports a role of CDKL2 in promoting EMT." (PMID 25333262, 2014). "According to the previous reports, CDKL2 is a newly discovered regulator enhancing EMT and increasing CD44-high subpopulation through upregulating ZEB1 expression in breast cancer." (PMID 33178818, 2020). "Cyclin-dependent kinase-like 2 (CDKL2) as a novel potent promoter for EMT and breast cancer progression." (PMID 25483103, 2015). "Subsequent characterization of candidate kinases led us to uncover cyclin-dependent kinase-like 2 (CDKL2) as a novel potent promoter for EMT and breast cancer progression." (PMID 25333262, 2014). "Taken together, our study uncovered a major role for CDKL2 in promoting EMT and breast cancer progression." (PMID 25333262, 2014). "In particular, we uncovered that serine/ threonine kinase cyclin-dependent kinase-like 2 (CDKL2) is a potent promoter for EMT and breast cancer progression." (PMID 25333262, 2014). "CDKL2 was recognized as a novel regulator of epithelial-mesenchymal transition (EMT) and demonstrated to enhance mesenchymal traits and stem-cell like phenotypes of breast cancer cells." (PMID 33178818, 2020). "Cyclin-dependent kinase-like 2 (CDKL2) is a member of the CDKL family and recognized as a novel regulator of epithelial-mesenchymal transition of breast cancer cells, but its role has not been explored in gastric cancer (GC)." (PMID 33178818, 2020).
gastric cancer (4 papers, 2018 to 2021). A primary or metastatic malignant neoplasm involving the stomach. "In gastric cancer, loss of CDKL2 expression was significantly correlated with clinicopathological characteristics (such as pathologic staging, histologic type, and grade); moreover, it could shorten patient disease-free survival and OS." (PMID 35096961, 2021). "Cyclin‐dependent kinase‐like 2 (CDKL2), a new member of the cyclin‐dependent kinase family, may be involved in gastric cancer (GC) progression." (PMID 29790675, 2018). "However, in gliomas, hepatocellular carcinoma, and gastric cancer, its underexpression or hypermethylation of its promoter indicates poor prognosis of patients; additionally, overexpression of CDKL2 in gastric cancer cells suppresses the growth and invasion of cancer cells." (PMID 33110456, 2020).
glioma (2 papers, 2020 to 2021). A benign or malignant brain and spinal cord tumor that arises from glial cells (astrocytes, oligodendrocytes, ependymal cells). "In addition, decreased CDKL2 expression predicted an evidently poor OS in glioma." (PMID 35096961, 2021). "They reported that the expression of CDKL2 in glioma tissues was significantly lower than that in non-cancerous brain tissues." (PMID 35096961, 2021).
invasive breast carcinoma (2 papers, 2014 to 2021). A carcinoma that infiltrates the breast parenchyma. "Although preliminary and need to be further validated, our results suggested CDKL2 can be a potential prognostic factor for worse outcome and therapeutic target for human invasive breast cancers." (PMID 25333262, 2014). "In human invasive breast cancers, overexpression of CDKL2 had a significantly shorter OS time." (PMID 35096961, 2021). "Notably, human invasive breast cancers with CDKL2 alterations, either amplification and/or elevated expression, had significantly shorter overall survival time." (PMID 25333262, 2014).
prostate carcinoma (2 papers, 2014 to 2021). A carcinoma that arises from epithelial cells of the prostate gland. "Indeed, prostate cancer epithelial cell line PC3 and pancreatic cancer epithelial cell line SU86.86 showed increased vimentin expression and enhanced migration ability with CDKL2 ectopic expression." (PMID 25333262, 2014).
cholangiocarcinoma (1 paper, 2021). A carcinoma that arises from the intrahepatic biliary tree (intrahepatic cholangiocarcinoma) or from the junction, or adjacent to the junction, of the right and left hepatic ducts (hilar cholangiocarcinoma). "Only in cholangiocarcinoma (CHOL) and pheochromocytoma and paraganglioma (PCPG), CDKL2 expression is up-regulated in tumor tissues." (PMID 35096961, 2021).
ciliopathies (1 paper, 2025). "However, patients with CDKL1 and CDKL2 variants have been reported that present with global developmental delay, intellectual disability, childhood-onset epilepsy, and dyspraxia—symptoms similar to those associated with CDD and other ciliopathies." (PMID 41385589, 2025).
developmental disabilities (1 paper, 2020). "Patients with mutations in CDKL2, CDKL3 or CDKL5 exhibit symptoms in intellectual and developmental disabilities." (PMID 32134924, 2020).
ovarian carcinoma (1 paper, 2010). A malignant neoplasm originating from the surface ovarian epithelium. "Somatic mutations in CDKL2 were nonsense and were only detected in breast and ovarian cancer cell lines or tumors." (PMID 21124932, 2010).
Subdural hemorrhage (1 paper, 2025). Hemorrhage occurring between the dura mater and the arachnoid mater. "Notably, 2 of the patients with CDKL2 variants show subdural hemorrhage and connective tissue defects, suggesting pleiotropic manifestations of CDKL2 variants." (PMID 41056017, 2025).
tumor (9 papers, 2010 to 2023). "Using 178 HC tissues, 169 adjacent non-tumor tissues and 24 normal liver tissues, it was revealed that CDKL2 methylation was associated with sex (p = 0.023), with methylation levels of CDKL2 appearing much higher in female patients (p = 0.037)." (PMID 37686484, 2023). "In this subgroup analysis, CDKL2 downregulation was associated with certain clinicopathological factors including gender, poor tumor grade, advanced TNM stages, positive nodal invasion, metastasis, tumor status, and survival of patients with ccRCC." (PMID 35096961, 2021). "Our findings may guide us to further investigate the importance/association of CDKL2 in ccRCC, the potential mechanism of CDKL2 expression, and immune interaction in tumor development and progression." (PMID 35096961, 2021). "Although differential expression of cyclin-dependent kinase-like 2 (CDKL2) has been reported to be associated with tumor progression in other cancers, its prognostic value, and potential mechanism in patients with ccRCC still remain unknown." (PMID 35096961, 2021). "For multivariate analysis, CDKL2 correlated independently with OS (HR = 0.764, CI: 0.602–0.970, p = 0.027), along with stage and tumor status." (PMID 35096961, 2021). "Similar to most studies, CDKL2 was considered a tumor suppressor gene and its upregulated expression was suggested to inhibit cancer cell proliferation and invasion." (PMID 35096961, 2021). "Gender, survival status, histologic grade, clinical stage, TNM classification, and tumor status were closely related to CDKL2 expression." (PMID 35096961, 2021). "Low expression of CDKL2 is positively correlated with tumor cell proliferation and invasion." (PMID 37308980, 2023). "Also, CDKL2 was expressed differently in tumor tissues of other organs and normal tissues, such as liver, lung, breast, brain, colon, rectum, uterus, bile duct, pancreas, stomach, and thyroid." (PMID 35096961, 2021). "It is possible that CDKL2 functions as a tumor suppressor in KIRC; however, this hypothesis requires further investigation through in vitro and in vivo studies." (PMID 33110456, 2020). "However, in this study, CDKL2 functioned as a tumor suppressor and enforced expression of CDKL2 inhibited GC cell proliferation and invasion." (PMID 29790675, 2018). "Therefore, expression of CDKL2 gene significantly increased tumor incidence of HMLER cells." (PMID 25333262, 2014). "According to the publicly available Oncomine database, the CDKL2 level in nontumor tissues is higher than that in tumor tissues in several cancers." (PMID 29790675, 2018). "Among the 151 tumor and nontumor pairs, 68 GC tissues (45.0%) showed low CDKL2 levels (scores of 0 or 1) and 89 nontumor tissues (58.9%) showed high CDKL2 levels (scores of 2 or 3)." (PMID 29790675, 2018). "They reported that compared to normal liver tissues, CDKL2 mRNA expression was downregulated in HCC cell lines and tumor tissues, which was inversely related to DNA methylation, suggesting that CDKL2 methylation may be involved in tumorigenesis and progression." (PMID 35096961, 2021).
cancer (5 papers, 2018 to 2021). A tumor composed of atypical neoplastic, often pleomorphic cells that invade other tissues. "We generated the ROC curve of CDKL2, age, grade, stage and cancer-status, the area under curve (AUC) was 0.703, 0.688, 0.732, 0.767, respectively." (PMID 35096961, 2021). "Gender, survival status, histologic grade, clinical stage, cancer status, and T, N, and M classification were significantly correlated with CDKL2 expression." (PMID 35096961, 2021). "Predictive model with nomograms integrating age, gender, grade, stage, cancer status, and CDKL2 expression level in TCGA dataset was generated; the c-index was 0.787." (PMID 35096961, 2021). "CDKL2 is known to be involved in cell proliferation in human cancer cells, while PER1 gene of the circadian clock is known to regulate cell proliferation and apoptosis in association with human cancer cells." (PMID 34785720, 2021). "AUC of combine model (CDKL2 + age + stage + grade + cancer-status) in TCGA was 0.856." (PMID 35096961, 2021). "The function of CDKL2 in different types of cancer is distinct." (PMID 33110456, 2020). "Although several studies till date have revealed that CDKL2 is essential for tumorigenesis and development, its role in cancer seems to be intricate without deep understanding." (PMID 35096961, 2021).
CDKL2 also shares sentences with these, for which no sentence is quoted: hepatocellular carcinoma (2 papers); adenocarcinoma (1); brain tumor (1); Clear Cell Renal Cell Carcinoma (1); colorectal cancer (1); developmental delay (1); dyspraxia (1); glioblastoma (1); Intellectual disability (1); kidney cancer (1); leukemia (1); lung carcinoma (1); pancreatic cancer (1); papillary serous adenocarcinoma (1); paraganglioma (1); pheochromocytoma (1); renal cell cancer (1); rheumatoid arthritis (1); thyroid carcinoma (1).